IL6 (interleukin 6)
Diseases named in the same sentence as IL6 in open-access papers (continued):
Sharing a sentence is not in itself a finding about the gene and the disease.
type 2 diabetes (continued). "Correlating these data, we can assume that CCL2, CCL5, IL-6, IL-1β, and leptin can play a significant role in MDSC recruitment in the adipose tissue of patients with type 2 diabetes." (PMID 39518420, 2024). "Sedentary behavior and the associated accumulation in visceral adiposity lead to increases in cytokines and inflammatory markers such as IL-6 and CRP, especially in patients with type 2 diabetes." (PMID 38725572, 2024). "Elevated levels of pro-inflammatory factors, including TNF-α, IL-6, and ICAM-1, can have a predictive role for the development of diabetic neuropathy in type 2 diabetic patients." (PMID 39596058, 2024). "Elevated levels of inflammatory markers such C-reactive protein (CRP), interleukin-6 (IL-6), and tumor necrosis factor-α (TNF-α) are commonly observed in patients with type 2 diabetes." (PMID 39224122, 2024). "Systemic levels of TNF-a, IL-1b, IL-6, and CRP are elevated in both type 1 and type 2 diabetes patients, which is a result of the chronic activation of pro-inflammatory pathways within insulin-target cells." (PMID 38904046, 2024). "After scaling in patients with type 2 diabetes, high-sensitivity C-reactive protein (hs-CRP), IL-1ß, IL-6 concentrations and HbA1c decreased." (PMID 38573898, 2024). "We evaluated the association of multiple thyroid parameters with the levels interleukin 6 (IL6) and interleukin 8 (IL8) in patients with euthyroid type 2 diabetes (T2D)." (PMID 39525855, 2024). "Clinical data also show that systemic levels of pro-inflammatory cytokines, including tumor necrosis factor (TNF)-a, interleukin (IL)-1b, IL-6, and CRP are elevated in patients with both type 1 and type 2 diabetes." (PMID 36769405, 2023). "In type II diabetes mellitus, dapagliflozin lowered CRP, IL-6 levels, and ferritin, though for CRP contradictory results exist." (PMID 37278822, 2023). "It has beneficial antidiabetic effects on type 2 diabetic rats by affecting the AMPK-mediated signaling pathway in the pancreas by inhibiting the production of TNF-α, IL-6, caspase-3, IL-1, and apoptosis, and restoring pancreatic beta cells." (PMID 37943820, 2023). "Previously, treatment with aqueous extract from Ajwa seed was seen to significantly decline brain COX-2, IL-6, and TNF-α levels in type 2 diabetic-induced rats." (PMID 36840284, 2023). "In four out of five cytokines (IL-6, IL-8, TNF-α, and IFN-γ), serum concentrations were higher in type 2 diabetes compared to type 1 (p < 0.003)." (PMID 37189645, 2023). "For instance, patients with type II diabetes mellitus exhibited the overexpression of various pro-inflammatory M1 polarisation markers [CD16, interleukin-6 (IL-6), iNOS, tumor necrosis factor-α (TNF-α), and CD36] in their PBMCs compared to healthy subjects." (PMID 37375598, 2023). "In patients with type 2 diabetes and CKD, dapagliflozin increased hemoglobin/hematocrit and reduced ferritin and urinary MCP-1/Cr and IL-6/Cr, suggesting potentially important effects on iron metabolism and inflammation." (PMID 38017482, 2023). "We previously reported that increased CATi and circulating IL-6 levels relate significantly to early mortality and ICU requirement during COVID-19 infection in patients with type 2 diabetes." (PMID 36587209, 2022). "The metabolic stress observed in type 2 diabetes can induce the pro-inflammatory cytokines, tumor necrosis factor-α (TNF-α) and interleukin-6 (IL-6), activating a series of complex processes leading to apoptotic death of pancreatic β cells." (PMID 35054822, 2022). "The activation of SOD and inhibition of MDA, IL-6, TNF-α, MCP-1 and cyclooxygenase-2 (COX-2) also indicated the mitigation of oxidative stress and inflammation, which is closely related to type 2 diabetes." (PMID 33435282, 2021). "Cytokines such as interleukin-6 (IL-6), tumor necrosis factor-α (TNF-α) and adiponectin (ADP) contribute to the development of type 2 diabetes (T2DM)." (PMID 34663293, 2021).
type 2 diabetes (continued). "The underlying mechanism may be related to inflammatory mediators including IL-6, IL-1α, and TNF-α, which not only promote epithelial–mesenchymal transition through activation of the Janus kinase/signal transducer and activator of trans-ions pathway but also increase the risk of type 2 diabetes." (PMID 34956904, 2021). "Treatment with SIT considerably decreased the gene expression of TNF-α and IL-6 in the adipose tissue of HFD and sucrose induced type-2 diabetic rats." (PMID 33917607, 2021). "An important observation in our study is that SIT acts as effectively as metformin to normalize the serum adipokine levels including leptin, resistin, adiponectin, TNF-α, IL-6, SREBP-1c and PPARγ in HFD and sucrose induced type 2 diabetic rats." (PMID 33917607, 2021). "In both the type 2 diabetes and metabolic syndrome models, treatment with the CCL4 antibody increased pancreatic insulin expression, and reduced circulating insulin, TNF-α, and IL-6 levels." (PMID 33968046, 2021). "In patients with type 2 diabetes, fat distribution is characterized by visceral (VAT) and ectopic adipose tissues expansion, resulting in an increased interleukin 6 (IL-6) release and systemic low-grade inflammation." (PMID 34384426, 2021). "This study investigated the association of selected salivary inflammatory biomarkers (Interleukin 6 [IL-6], C-reactive protein [CRP], and Tumour necrosis factor α [TNF-α]) to glycated haemoglobin (HbA1C) in type 2 diabetics." (PMID 33676486, 2021). "In obese patients with concomitant type 2 diabetes, A-FABP levels were further elevated and significantly correlated with levels of inflammatory cytokines, including C-reactive protein and interleukin-6 (IL-6)." (PMID 34502295, 2021). "According to the authors, naringin attenuated hyperglycemia-mediated oxidative stress parameters (MDA and NO) and pro-inflammatory cytokine (TNF-α and IL-6) secretion and production in HFD/STZ-induced type 2 diabetic rats." (PMID 32977511, 2020). "Although we cannot exclude the possibility that IL-6 levels may have been impacted by acute infections at baseline, to affect the observational results presented, IL-6 levels would have to differ significantly at the time of prospective type 2 diabetes diagnosis to have an effect." (PMID 33096487, 2020). "Type 2 diabetes patients with CRC had higher triglyceride, total cholesterol, IL-6, and circulating sRAGE levels and lower use of medicines than type 2 diabetes patients without CRC." (PMID 33187505, 2020). "We also found that ouabain (100 nM) promoted the secretion of IL-6, IL-8, GM-CSF, and TNF-α from the skeletal muscle cells of healthy subjects, and the secretion of GM-CSF from cells of subjects with the type 2 diabetes." (PMID 33101052, 2020). "Our trial showed that 3 g of cinnamon supplementation for 8 weeks had no beneficial impacts on plasma levels of NF-kB, SIRT1 and systemic inflammation factors including hs-CRP, IL-6 and TNF-α in type 2 diabetic patients." (PMID 31901246, 2020). "This systemic overabundance of proinflammatory cytokines in adipose tissue, including IL-6, activates STAT3 and subsequently AMPK leading to alterations in insulin signaling and eventually Type 2 diabetes." (PMID 32878032, 2020). "Importantly, exposure to inflammatory cytokines, such as TNF and IL-6, and activation of NF-κB in muscle can decrease oxidative metabolism, induce atrophy, and prevent insulin-stimulated Akt phosphorylation, all of which are factors in the development of type 2 diabetes and metabolic syndrome." (PMID 32591558, 2020). "The present results revealed that B. vernae extract could significantly reduce the TNF-α, IL-1β, and IL-6 levels of diabetic rats, suggesting that B. vernae might have potential anti-inflammation activity, which is beneficial to improve the inflammatory state of type 2 diabetes." (PMID 32636751, 2020).
type 2 diabetes (continued). "Our purpose was to evaluate the effect of daily supplementation of three-gram cinnamon on plasma levels of NF-kB, SIRT, hs-CRP, IL-6 and TNF-α among type 2 diabetes patients." (PMID 31901246, 2020). "Thus, Qi and colleagues could not find any substantial association of type 2 diabetes risk with both circulating interleukin level and polymorphisms in IL6, including rs1800795." (PMID 32961860, 2020). "Our purpose was to evaluate the effect of cinnamon supplementation on NF-kB, SIRT1 and systemic inflammation factors (hs-CRP, IL-6 and TNF-α) levels among type 2 diabetes patients." (PMID 31901246, 2020). "IL-6, leptin, and RBP4 levels were higher in those who developed type 2 diabetes than in the other groups." (PMID 31690939, 2020). "In type-2 diabetic patients, TNF-α was significantly decreased after the treatment with Brazilian green propolis, however IL-1β and IL-6 were significantly increased." (PMID 31717277, 2019). "Increased production of proinflammatory cytokines, such as IL‐6 and TNF‐α, plays an important role in the pathogenesis of type 2 diabetes and contributes to long‐term micro and macrovascular complications." (PMID 31183921, 2019). "We assessed interleukin‐6 (IL‐6), interleukin‐1 receptor antagonist (IL‐1RA), monocyte chemoattractant protein‐1 (MCP‐1), and cortisol responses to acute stress in 135 people with Type 2 diabetes." (PMID 30693534, 2019). "In conclusion, this study shows that canagliflozin treatment decreases the plasma concentration of TNFR1, IL-6, MMP7 and FN1 in individuals with type 2 diabetes and elevated albuminuria." (PMID 31001673, 2019). "An increase in the circulating levels of IL-6 and MCP from various lipogenic tissues, including adipose and liver tissues, has been shown to be a predictor of type 2 diabetes progression." (PMID 27929393, 2016). "We found that metformin reduced the levels of IL-6 in blood and MCP-1 in urine, but increased IL-10 levels in blood of patients with type 2 diabetes." (PMID 27904436, 2016). "A-FABP was significantly correlated with glycated hemoglobin A1C (HbA1C), BMI, triglyceride, Homeostasis Model Assessment Index (HOMA-IR), waist hip rate, C-reactive protein, IL-6, and HDL-C in obese subjects with type 2 diabetes." (PMID 27819006, 2016). "Clinically NF-κB related cytokines, TNF-α, IL-6, and MCP-1, were found increased in patients with type 2 diabetes." (PMID 27656261, 2016). "The results of the current study showed that HbA1C, BMI, TG, HOMA-IR, WHR, CRP, and IL-6 were positively correlated with serum A-FABP, and HDL-C was negatively correlated with A-FABP in obese subjects with newly diagnosed type 2 diabetes." (PMID 27819006, 2016). "In the present study, we determined the effects of metformin on the levels of pro-inflammatory cytokines (i.e., IL-6, TNF-α, and MCP-1) and anti-inflammatory mediator IL-10 in blood and urine of patients with type 2 diabetes." (PMID 27904436, 2016). "In comparison with gliclazide, acarbose, and repaglinide, metformin reduced the levels of serum IL-6, TNF-α, and urinary MCP-1 in patients with type 2 diabetes." (PMID 27904436, 2016). "In the present study, we determined the effects of metformin with different doses and durations on the levels of pro-inflammatory cytokines (i.e., IL-6, TNF-α, and MCP-1) and anti-inflammatory mediator IL-10 in blood and urine of patients with type 2 diabetes." (PMID 27904436, 2016). "Elevated serum levels of innate immunity inflammatory cytokines such as IL-6, IL-18 and TNF-α have been reported for subjects with type 2 diabetes and related complications." (PMID 28536605, 2016). "Our results indicated that significant increases in the levels of pro-inflammatory cytokines, TNF- α IL-6 and also CRP were observed in obese and type 2 diabetic rats and were consistent with other studies." (PMID 26003803, 2015).
type 2 diabetes (continued). "FMD, S(I), and adiponectin levels resulted significantly lower in patients with type 2 diabetes mellitus, whereas TNF-a and IL-6 levels have been observed as significantly higher in the same diabetic patients." (PMID 25883983, 2015). "An improved understanding of the mechanisms behind IL‐6 signaling within the complex model of high‐fat diet (HFD) and physical activity is required to develop improved treatment strategies for type 2 diabetes." (PMID 24997069, 2014). "A growing number of studies have confirmed that many types of inflammatory factors can predict the occurrence of type 2 diabetes, such as TNF-α and IL-6." (PMID 24633252, 2014). "Our group has previously shown that interleukin (IL)-6 and activin A, a member of the transforming growth factor β superfamily, are related to the degree of CAD in patients with type 2 diabetes." (PMID 23987834, 2013). "In persons with type 2 diabetes or impaired glucose tolerance, the correlation coefficient for CRP and IL-6 was reported to be in a similar range (r = 0.49)." (PMID 23991111, 2013). "The healthy controls and patients with type 2 diabetes were divided into low (QL) and high (QH) muscle content of myostatin mRNA and the fasting glucose, insulin, HOMA2-IR, and plasma IL-6 levels were compared." (PMID 22615949, 2012). "Regarding inflammatory biomarkers (IL-6 and TNF-α), type 2 diabetes patients had higher levels compared with NGT subjects." (PMID 23251434, 2012). "Participants who developed type 2 diabetes during follow-up had significantly higher levels of IL-6, hs-CRP, leptin and γGT, and lower levels of adiponectin than participants who remained free from type 2 diabetes." (PMID 23251619, 2012). "In this report, we have shown significantly higher serum concentrations of inflammatory markers (IL-6, hs-CRP, and Hp) in type 2 diabetics compared to controls." (PMID 23283045, 2012). "Serum levels of the inflammatory markers (IL-6, hs-CRP, Hp) were significantly increased (p = .000.019, and .000 respectively) in type 2 diabetics compared to control subjects." (PMID 23283045, 2012). "On univariate analysis, participants who developed type 2 diabetes had significantly higher baseline levels of IL-6, CRP, leptin and γGT, and lower levels of adiponectin than participants who remained free of type 2 diabetes." (PMID 23251619, 2012). "In patients with type 2 diabetes, the use of Anakinra (IL-1Ra) improved glycemia and beta-cell secretory function and reduced markers of systemic inflammation (CRP, IL-6)." (PMID 21410952, 2011). "In contrast, H3K9 tri-methylation levels are significantly decreased at the promoters of key inflammatory genes IL-6, MCSF and MCP-1 promoters in vascular smooth muscle cells of mice with a type 2 diabetes-like condition." (PMID 21192791, 2010). "In contrast to IL-6 and TNF-α, adiponectin mRNA is reduced in adipose tissue from patients with type 2 diabetes." (PMID 20671994, 2010). "In the present study, we have demonstratedthat in type 2 diabetes, there is an increased mRNA expression of resistin,along with significant increases in TNF-α, IL-6, and Il-1β mRNA expression bythe peripheral circulating mononuclear cells." (PMID 19125180, 2008). "Of interest, inflammatory markers (C-reactive protein (CRP) and Interleukin-6 (IL-6)) and glucagon-like peptide-1 (GLP-1) levels were similarly elevated across all subtypes compared to controls, indicating common aspects in Type 2 diabetes molecular pathology despite different clinical phenotypes." (PMID 40022072, 2025). "Furthermore, another study found a significant link between increased AAR and the levels of inflammatory cytokines such as IL-4, IL-6, and TNF-α in type 2 diabetes." (PMID 40408358, 2025).
type 2 diabetes (continued). "Studies involving patients with type 2 diabetes have shown that daily γ-oryzanol intake reduces systemic inflammatory markers such as C-reactive protein (CRP), interleukin-6 (IL-6), and interferon-gamma (IFN-γ), indicating its anti-inflammatory efficacy in metabolic contexts." (PMID 41009004, 2025). "We found that at the end of treatment, XOMA052 was able to alleviate chronic inflammation in type 2 diabetes by down-regulating the production of IFN-γ and IL-17a in peripheral blood, reducing inflammatory cytokines TNF-α, IL-1β, and IL-6, and reducing β cell apoptosis and promoting proliferation." (PMID 40066372, 2025). "Peripheral levels of Interleukin-1β (IL-1β), Interleukin-6 (IL-6), and tumor necrosis factor-α (TNF-α) are elevated during first-episode psychosis and psychotic relapses in schizophrenia, as well as in the pathogenesis and complications of type 2 diabetes." (PMID 40426670, 2025). "Participants with type 2 diabetes who consumed oleocanthal-enriched HP-EVOO experienced enhanced antiplatelet effects, lower inflammatory cytokine levels (TNF-α, IL-1β, and IL-6, p < 0.05) and enhanced anti-inflammatory IL-10 concentration (p = 0.032) compared to butter, olive oil and EVOO groups." (PMID 40136590, 2025). "However, in individuals with inflammatory bowel disease, type 2 diabetes, and coronary artery disease serum Metrnl levels showed a significant negative correlation with serum inflammatory cytokines (TNF-α, IL-6)." (PMID 39964474, 2025). "In vitro and in vivo studies show that muscle-derived IL-6 enhances lipolysis and fat oxidation through a mechanism involving AMPK activation and that IL-6 autoantibodies appear to be involved in the pathogenesis of type 2 diabetes." (PMID 39125786, 2024). "Inflammation markers like IL-6 and CRP are related to heart disease and type 2 diabetes." (PMID 39685657, 2024). "Specifically, the levels of interleukin 6 (IL6) and IL8 have strong correlations with the level of glycated hemoglobin (HbA1c) and with subsequent cardiovascular and renal complications in individuals with type 2 diabetes (T2D)." (PMID 39525855, 2024). "It was observed that serum IL-6, IL-8, ICAM and VCAM levels in type II diabetes mellitus (T2DM) with PAD patients were increased significantly (85.93, 597.08, 94.80 and 80.66) as compared to T2DM patients (59.52, 231.34, 56.88 and 50.19) and healthy individuals (4.81, 16.93, 5.55 and 5.16)." (PMID 38961103, 2024). "In addition to Aβ accumulation, previous studies illustrated an increase in levels of proinflammatory cytokines such as IL-1β, IL-6, and TNF-α in patients with type 2 diabetes." (PMID 38510866, 2024). "Consistent with metformin as a treatment for type 2 diabetes, pure C15:0 has been shown to improve glucose uptake by cells, and supplementation over 12 weeks effectively lowers glucose, cholesterol, MCP-1, and IL-6 in a high-fat diet-induced mouse model of type 2 diabetes." (PMID 37960259, 2023). "However, in our cohorts, pro-inflammatory cytokines IL-6, IL-8, TNF-α, and IFN-γ were significantly higher in type 2 diabetes compared to type 1, which is consistent with previous findings." (PMID 37189645, 2023). "(2018) reported that dietary supplementation of L-carnosine (500 mg/kg) resulted in decreased fasting glucose and HbA1c levels, as well as increased serum TG and HDL levels in patients with type 2 diabetes, without affecting IL-6 and IL-1β levels." (PMID 38198911, 2023). "Visceral white adipose tissue (abdomen and upper body) appears to be the major source of inflammatory markers in type 2 diabetes (cytokines, TNF-alpha, IL-1, IL-6, IL-10, leptin, adiponectin, monocyte chemoattractant protein, angiotensinogen, resistin, chemokines, etc.)." (PMID 37298118, 2023). "In type 2 diabetes and HTN, obesity and overweight, insulin resistance, and overexpression of pro-inflammatory proteins including C-reactive protein (CRP) and cytokines (IL-1β, IL-6, and TNF-α) contribute to chronic inflammation." (PMID 35361279, 2022).